SIRT1 (sirtuin 1)
Diseases named in the same sentence as SIRT1 in open-access papers (continued):
Sharing a sentence is not in itself a finding about the gene and the disease.
tumor (continued). "Overall, SIRT1 may function as both an oncogene and tumor suppressor depending on subcellular localization, age, type of tissue, and concomitant mutations in related signaling pathways." (PMID 31608282, 2019). "SIRT1 was first found as a nuclear protein that may also shuttle to the cytoplasm during neuronal differentiation and neurite outgrowth, tumour progression and apoptosis." (PMID 31747893, 2019). "Directly inhibiting SIRT1 via miRs, exogenous compounds, or combining conventional chemotherapeutics with tumor-selective SIRT1 inhibitors may improve treatment outcomes." (PMID 31608282, 2019). "SIRT1 has long been recognized as both a tumor promoter and tumor suppressor." (PMID 30930849, 2019). "Although, in HCC cells, SIRT1 had a predominant nuclear localization where its expression promotes tumorigenesis, it was reported that cytoplasmatic SIRT1 may have tumor-suppressive roles." (PMID 31608282, 2019). "Thus, SIRT1 can function either as a promoter or a suppressor in chemotherapy resistance, depending on the tumor types, cellular background, or microenvironment." (PMID 30697969, 2019). "By performing unbiased proteomic approaches, we found that SIRT1 might regulate tumor progression via an EMT process." (PMID 31317367, 2019). "Many previous reports have shown that SIRT1 is a tumor suppressor." (PMID 30902968, 2019). "In the current study, we endeavored to elaborate the biological correlation between ADC values and SIRT1 protein levels in tumour tissues in patients with ESCC, because SIRT1 was documented to be related to chemoradiation resistance by several studies including our preliminary studies." (PMID 31684999, 2019). "In non-tumor cells, it has been shown to be upregulated by melatonin and effects by melatonin have been repeatedly reported to be suppressed by sirtuin inhibitors or Sirt1 siRNA, notably also in an anti-inflammatory context." (PMID 30862067, 2019). "Our present results agree with the previous findings by showing that the SIRT1-inhibition-mediated enhancement of c-Myc acetylation is accompanied by up-regulation of TRAIL and DR5, supporting the idea that SIRT1 plays a tumor-promoting role in the context of c-Myc activation." (PMID 30909652, 2019). "Sirt1, the mouse homologue of yeast Sir2 deacetylates several non-histone proteins and plays roles in many key functions, including energy metabolism, differentiation, aging, and tumor suppression." (PMID 30630525, 2019). "Surprisingly, some studies report an opposing role for SIRT1 in the same tumor types." (PMID 30761005, 2019). "To date, the role of SIRT1 in tumor progression remains controversial." (PMID 31317367, 2019). "The nucleocytoplasmic shuttling of SIRT1 was discovered more than a decade ago, but the roles of subcellular SIRT1 localization in tumor progression remain unclear." (PMID 31317367, 2019). "Based on these findings, we asked whether modification of SIRT1 protein or activity could alter tumor cell response to sorafenib in HCC cell lines." (PMID 31430957, 2019). "Conversely, some reports propose that SIRT1 is a tumor promoter." (PMID 31317367, 2019). "On the other hand, sirtuin-1 may also play a role in the regulation of tumor microenvironment of the immune cells." (PMID 31487876, 2019). "Moreover, CDK2 and SIRT1 expression in the tumor pieces of these patients tended to directly, while CDKN2A inversely, be correlated with GOAT urine levels." (PMID 31766715, 2019). "While it was proposed that tumor cells act through SIRT1-regulated pathways by preventing aberrant life cycle, the main role of SIRT1 remains unclear." (PMID 31747893, 2019).
tumor (continued). "There are several possible mechanisms involved in SIRT1 mediated tumor progression." (PMID 29636061, 2018). "Consequently, SIRT1 detection has potential to become a powerful prognostic indicator for tumor evolution and response to chemotherapeutics." (PMID 30319540, 2018). "Moreover, the regulation is further validated in HCC tumor and peritumoral tissues, a lower level of SIRT1 protein corresponded with a higher level of CPEB1 in the same visual field of peritumoral tissues, and vice versa in the HCC tumor tissues." (PMID 30237545, 2018). "In addition, SIRT1 inactivation eliminates estrogen/ER-α-induced cell growth and tumor development, triggering apoptosis and cell growth arrest." (PMID 30380732, 2018). "Per BC tumor progression, it is speculated whether SIRT1 has a role in determining tumor conversion to a drug-refractory phenotype." (PMID 30319540, 2018). "In addition, a stable expression of miR-34a or silencing of SIRT1 reduces tumor growth in nude mice xenografts." (PMID 30380732, 2018). "According to these, it remains controversial whether SIRT1 acts as an oncogene or tumor-suppressor, and its specific functions may depend on diverse biological signaling." (PMID 30451820, 2018). "SIRT1 also downregulates the activity of the tumor-suppressing retinoblastoma protein (Rb)." (PMID 30380732, 2018). "Furthermore, knockout mice models of SIRT1 are prone to tumor development, which points to a tumor-suppressive SIRT1 action." (PMID 29340027, 2017). "Moreover, in vivo chondrosarcoma xenograft study revealed a dramatic reduction in tumor volume and the increased SIRT1 and cleaved caspase-3 expressions in tumors by resveratrol treatment." (PMID 28600541, 2017). "However, the role of SIRT1 in oncogenic and tumor-suppressive function in chondrosaroma still remains to be clarified." (PMID 28600541, 2017). "Activation of SIRT1 promotes tumor cell migration and lung metastasis of breast cancer in mice." (PMID 29312612, 2017). "Our work presented herein explored how SIRT1 suppressed TIMP1 by impeding the binding of transcription factor specificity protein 1 (Sp1) to the TIMP1 promoter (pTIMP1) as well as what molecular mechanisms contributed to the tumor-like invasion of RA FLSs." (PMID 29179491, 2017). "It is possible that SIRT1 downregulation facilitates tumor cells to undergo mitophagy, which may be a protective response to survive metabolic stresses." (PMID 28052003, 2017). "The exactly effect of SIRT1 in tumor development is still controversial." (PMID 28112277, 2017). "So we speculated that down-regulation of SIRT1 resulted in oxidative stress and further promoted hepatocarcinogenesis as aging, and resveratrol inhibited spontaneous neoplasms by up-regulation of SIRT1 and decrease of oxidative stress in the annual fish." (PMID 28903430, 2017). "Results showed that resveratrol negatively regulated expression of Ac-FoxO1 and p-FoxO3a (p<0.01), revealing that resveratrol decreased phosphorylation of FoxO3a (by inactivating K-Ras/PI3K/AKT signal) and acetylation of FoxO1 with SIRT1 up-regulation to induce apoptosis in spontaneous neoplasms." (PMID 28903430, 2017). "Similar to SIRT1, DNMT3B was stronger associated with Mxd1 in the tumor cell lines." (PMID 29383100, 2017). "Thus, SIRT1 inhibition is believed to exert anticancer effects against HCC by way of inhibiting these tumor promoting signaling pathways as well as inhibiting EMT." (PMID 27935857, 2017).
tumor (continued). "These seemingly opposite functions might reflect a highly context-specific role of SIRT1 as a tumor-suppressor versus tumor-promotor." (PMID 29340027, 2017). "SIRT1 was identified as a direct target for miR-22, and miR-22 might act as a tumor suppressor in RCC and blocks RCC growth and metastasis by direct targeting of SIRT1, indicating a potential new therapeutic effect in RCC therapy." (PMID 28986523, 2017). "SIRT1 regulates a variety of physiological processes, including stress responses, metabolism, apoptosis, calorie restriction and aging Because SIRT1 allows the histones to wrap DNA more tightly, it favors tumor progression by inhibiting the expression of tumor suppressor genes in malignant cells." (PMID 27935857, 2017). "In order to assess whether SIRT1 deacetylated K-Ras in spontaneous neoplasms of the annual fish, we examined acetylation of K-Ras by immunoprecipitating equal amount of K-Ras protein (using few beads incubated with excess total proteins)." (PMID 28903430, 2017). "In addition, SIRT1 is found to promote angiogenesis as well, which is a characteristic in favor of tumor growth." (PMID 27659520, 2017). "There was also a significant difference between serum SIRT1 levels in different tumor grades, graded according to the modified Bloom–Richardson system, as manifested by a higher SIRT1 level in grade 2 compared to grade 1 patients, and a higher value in grade 3 than in grade 2 patients (p < 0.05)." (PMID 26999517, 2016). "Our preliminary results suggest that MSCs-Sirt1 may represent a promising strategy for tumor treatment in the clinic." (PMID 27782173, 2016). "Next, we investigated whether downregulation of Sirt1 by mRNA modulates the anti-tumor effects of resveratrol against CRC migration and invasion in the 3D alginate-based culture microenvironment, by evaluating through toluidine blue staining." (PMID 26959057, 2016). "However, when RM-1 or PC2 cells were co-injected with MSCs-Sirt1, tumor weights showed a significant reduction." (PMID 27764779, 2016). "Expression of CXCL10 mRNA was also increased in tumor tissues of MSCs-Sirt1 group." (PMID 27764779, 2016). "However, recent studies also support SIRT1 as a tumor suppressor which inhibits several oncogenic proteins such as NF‐κB, β‐catenin, and survivin under certain circumstances." (PMID 27613566, 2016). "At the end of experiment, we proved the existence of MSCs-Sirt1 in tumor tissues." (PMID 27764779, 2016). "SIRT1 suppresses tumor formation and growth by preventing genotoxic stress and inducing apoptosis." (PMID 26992208, 2016). "SIRT1 overexpression is associated with a higher α-fetoprotein level, higher tumour grade, and absence of a β-catenin mutation." (PMID 27793039, 2016). "SIRT1 regulates many tumor suppressors and DNA repair genes." (PMID 27226812, 2016). "Similarly, depletion of NK cells significantly weakened the antitumor effect, confirming that NK cells were critical to the MSCs-Sirt1-induced antitumor effect in tumor-bearing mice." (PMID 27764779, 2016). "However, when 4T1 cells were coinjected with MSCs-Sirt1, tumor showed a significant reduction in weight." (PMID 27782173, 2016). "However, we found the remarkable positive correlation between MEK1/SIRT1 expression and tumor size (p = 0.012), vascular invasion (p < 0.001), capsular invasion (p = 0.048) and clinical tumor stage (p < 0.001)." (PMID 26967560, 2016). "Our data demonstrated increased levels of CXCL10 in serum and tumor tissues of MSCs-Sirt1 mice." (PMID 27764779, 2016).
tumor (continued). "Because of the link between glycolytic metabolism, tumor formation and tumor cell growth, we set out to explore whether these mechanisms were regulated by SIRT1 in the pancreas." (PMID 27494892, 2016). "In this study, we found that SIRT1 directly binds to and deacetylates FOXM1, and participates in regulating FOXM1 acetylation status during cell cycle and FOXM1 transcriptional activities, indicating that SIRT1 acts as a tumor suppressor in regulating FOXM1 activity." (PMID 27542221, 2016). "Sirt1 and the other Sirts have been shown to have both pro- and anticarcinogenic effects by improving genetic stability and regulating pathways that contribute to tumor suppression." (PMID 27379175, 2016). "However, upon oncogenic events, tumor cells co-opt SIRT1-regulated cellular pathways to promote unabated proliferation, progression, resisting death signals, and genetic/epigenetic evolution." (PMID 26999517, 2016). "According to previous studies, it remains controversial whether SIRT1 acts as a tumour promoter or suppressor." (PMID 27793039, 2016). "Indeed, it has been reported that Sirt1 blocks NF-κB signaling pathway activation, which induces inflammation and tumor invasion." (PMID 26959057, 2016). "In order to confirm whether NK cells induced local inflammatory response and performed the effect of MSCs-Sirt1-induced tumor suppression in tumor-bearing mice, tumor-infiltrating NK cells were isolated and analyzed by flow cytometry." (PMID 27782173, 2016). "Downregulation of SIRT1 by small hairpin (sh)-RNA increased E-cadherin expression while reducing tumor cell proliferation, invasion, metalloproteinase (MMP) expression, and capacity to form tumors in vivo, thus emphasizing the active role of the histone deacetylase in EMT induction." (PMID 27379175, 2016). "In HCC, SIRT1 is aberrantly overexpressed and plays an important role in maintaining tumor growth." (PMID 26824501, 2016). "Based on the evidence, autophagic process, modulated by SIRT1 or other mediators may play a central role in tumor progression by regulating EMT and tumor cell invasion." (PMID 26910278, 2016). "Our results show that MSCs-Sirt1 inhibit PCa tumor growth, suggesting that they might represent a new potential strategy for PCa therapy." (PMID 27764779, 2016). "Furthermore, through Human Tumor Metastasis PCR Array we discovered KISS1 was one of the downstream targets of SIRT1." (PMID 27145368, 2016). "Similarly, depletion of NK cells significantly weakened the antitumor effect, establishing that NK cells were critical to the antitumor effects of MSCs-Sirt1 in tumor-bearing mice." (PMID 27782173, 2016). "Interestingly, many of the metabolic pathways that are influenced by SIRT1 are also altered in tumor development." (PMID 25569080, 2015). "A number of tumors exhibit an altered expression of sirtuins, including NAD+-dependent histone deacetylase silent information regulator 1 (SIRT1) that may act as a tumor suppressor or tumor promoter mainly depending on the tumor types." (PMID 26225773, 2015). "To further determine whether modulation of miR-34a-SIRT1 axis can inhibit tumorigenesis and tumor growth in vivo, we inoculated 5 × 105 cells stably transfected with either lentivirus-miR-34a or shRNA-SIRT1, into mouse mammary fat pad." (PMID 25826085, 2015).
tumor (continued). "Furthermore, there are new evidences that SIRT1 acts as a tumor suppressor based on its role in negatively regulating beta-catenin and survivin." (PMID 25605253, 2015). "A similar pattern was also observed for SIRT1 expression in the tumor tissues." (PMID 25895126, 2015). "By contrast, knocking down SIRT1 sensitized tumor cells to CPZ treatment." (PMID 26363315, 2015). "In nude mice xenografts, stable expression of miR-34a and silencing of SIRT1 reduced tumor burden." (PMID 25826085, 2015). "Altogether, metabolomic data suggest that a decreased GPChol/PChol ratio isassociated with high-grade tumors and that the expression of HDAC1,HDAC4 and SIRT1 may influence tumor aggressiveness throughchanges in metabolomic profiles of tumors." (PMID 25791281, 2015). "Of note, increased Cyclin D1, Ki-67 and SIRT1 protein levels were found in tumor homogenates obtained from G-1 stimulated mice with respect to mice treated with vehicle, however, these stimulatory effects were prevented in the group of animals receiving G-1 in combination with Sirtinol." (PMID 26225773, 2015). "Moreover, SIRT1 protein expression was significantly elevated in advanced tumor stages (75%, 37 of 49 cases) compared with that in stage I + II (54%, 31 of 57 cases)." (PMID 26363315, 2015). "In this study we tested whether curcumin, through increasing SIRT1 activity, could modulate SIRT1 functions in vitro and in vivo and ultimately impact on the regulation of tumor formation and growth." (PMID 26299580, 2015). "Indeed, therole of the deacetylase activity of SIRT1 in tumor growth and metastasis wasrecently challenged by observations that the catalytic activity of SIRT1 haslittle effect on tumor growth and metastasis in a mouse tumor model." (PMID 25923013, 2015). "Together with our previous findings in chemoprevention studies, these results indicate that MSC enhances NAD+/NADH oscillation and SIRT1 activity to increase circadian expression of genes involved in DNA repair and tumor suppression, contributing to early barrier to tumorigenesis." (PMID 26544624, 2015). "From these data, SIRT1 has been suggested to exhibit tumor-promoting functions in the cell." (PMID 25486244, 2014). "In addition, experiments with a mouse model revealed that SIRT1 overexpression enhanced HCC tumor metastasis in vivo." (PMID 25522783, 2014). "Finally, combined expression levels of the histone-modifying enzymes LSD1, HDAC2 and SIRT1 correlated with tumor differentiation and tumor cell proliferation." (PMID 25139823, 2014). "The outcome of these studies showed both tumor promoting and inhibiting effects related to Sirt1." (PMID 25013930, 2014). "Furthermore, we demonstrated that SIRT1 expression levels were significantly increased in tumor tissues compared to normal epithelial breast tissues, which has also been described in literature." (PMID 25139823, 2014). "The effects of estrogen receptor activation are dependent on the dosage of its cognate gene suggesting that the tumor promotion seen with resveratrol in Sirt1Y/+ animals may be a result of SIRT1 dosage-dependent modulation of estrogen receptor signalling." (PMID 25380034, 2014). "Notably, previous data have indicated that Sirt1 is both a tumor promoter and a tumor suppressor in tumorigenesis." (PMID 24959282, 2014). "HFD decreased tumor latency in both Sirt1+/+ and Sirt1Y/Y mice." (PMID 25380034, 2014). "Taken together, these results support the hypothesis that SIRT1 may promote tumor progression partially by induction of lymphangiogenesis and LVI." (PMID 25922660, 2014).